INS (insulin)
Diseases named in the same sentence as INS in open-access papers (continued):
Sharing a sentence is not in itself a finding about the gene and the disease.
Hypoglycemia (continued). "Hypoglycemia occurs because too much insulin is injected into the body." (PMID 36793281, 2023). "This relatively high frequency of postprandial hypoglycemia could be attributed to the delayed gastric emptying effect of dietary fat and the increased insulin doses used with the meals." (PMID 40303273, 2023). "However, untreated microneedles prepared with pure silk fibroin are prone to break and dissolve rapidly, which can lead to a burst of insulin release and hypoglycemia." (PMID 36839676, 2023). "Basal insulin (BI) therapy is a widely used option among available insulin therapies and requires a balance between achieving individualized glycemic targets and reducing hypoglycemia." (PMID 36624651, 2023). "We hoped to provide easier insulin application and titration, with avoidance of hypoglycemia." (PMID 37476884, 2023). "In addition, to mitigate the adverse effect of hypoglycemia on patients, it is also of significance to monitor the real-time blood glucose changes during intensive insulin therapy." (PMID 38223574, 2023). "Due to the predominantly postprandial occurrence of PBH and the well-established differences in counter-regulatory responses to insulin-induced hypoglycaemia in the fasting vs postprandial state, we performed the clamp experiment after the ingestion of 15 g of glucose." (PMID 36648553, 2023). "More advanced technologies including automated insulin delivery systems with ability to attenuate or suspend insulin delivery for down trending glucose may further improve hypoglycemia confidence." (PMID 40303243, 2023). "Our findings are in line with pre-existing literature and we speculate that they may suggest a global attenuation of neurohormonal responses to insulin-induced hypoglycaemia in post-bariatric surgery patients experiencing substantial weight loss." (PMID 36648553, 2023). "Other characteristics of PAI include spontaneous episodes of hypoglycemia or an unexplained decrease in the insulin dose requirement in a person with diabetes mellitus, and in women, axillary and pubic hair loss owing to insufficient adrenal androgen production." (PMID 37238296, 2023). "In addition, continuous glucose monitoring (CGM) revealed that insulin-treated patients with T2DM are prone to develop hypoglycemia, many episodes of which are asymptomatic." (PMID 37675290, 2023). "Since both hGH and IGF-1 have a direct influence on glucose metabolism, mimicking the anabolic effect of insulin, and because hypoglycemia is a potential side effect in individuals treated with IGF-1, we correlated the metabolic response to these two compounds to the baseline glucose metabolism." (PMID 36833418, 2023). "This could be due to the fact that individuals with kidney damage are more likely to experience hypoglycemia when taking insulin." (PMID 37089510, 2023). "Hypoinsulinaemic (suppressed insulin and c-peptide) hypoglycaemia typically occurs spontaneously or may be provoked by fasting." (PMID 37892096, 2023). "It is evident that insulin detemir implemented as an add-on therapy to OADs improved glycemic control without increased risk of hypoglycemia, adverse events or body weight compared with baseline." (PMID 36624650, 2023). "It is, therefore, essential that laboratories investigating hypoglycaemia offer, as a minimum, the measurement of insulin, C-peptide and proinsulin as an inconsistency in the results could point to immunoassay interference in an assay." (PMID 37892096, 2023). "It is worth remembering that insulin and other medications may need to be adjusted to prevent hypoglycemia and blood pressure." (PMID 38140355, 2023). "Importantly, contributions of ghrelin to the insulin-induced hypoglycemia CRR also have been identified." (PMID 37334290, 2023). "Snacks with carbohydrates are mainly advocated in insulin-treated patients to prevent hypoglycemia." (PMID 37885536, 2023). "However, the subcutaneous injection of insulin is easy to peak at night, making patients produce hypoglycemia." (PMID 37514488, 2023).
Hypoglycemia (continued). "Group A revealed to feel more confident in the management of children with T1D during scholastic (p = 0.006) and extra-scholastic activities (p = 0.01), in supporting the children in the administration of insulin (p < 0.001) and in recognizing hypoglycaemia (p = 0.006)." (PMID 38239792, 2023). "However, weight loss can be achieved with regular training, particularly if small reductions in total daily insulin dosages occur and excessive energy intake to prevent and/or treat hypoglycemia is generally avoided." (PMID 37299463, 2023). "However, after birth, these infants are no longer exposed to the high glucose levels from their mothers, but continue to produce high levels of insulin, which can result in hypoglycemia." (PMID 37529595, 2023). "SIRT6 deficiency increases insulin-stimulated glucose uptake by activating insulin signaling, which may be involved in severe hypoglycemia in global Sirt6 KO mice." (PMID 38201252, 2023). "The Hypoglycaemia – MEasurement, ThResholds and ImpaCtS (Hypo-METRICS) app was developed for research purposes and uses ecological momentary assessments (EMAs) to capture the impact of hypoglycemia on daily functioning in adults with T1DM or insulin-treated T2DM." (PMID 37773626, 2023). "However, no significant change in circulating AM concentrations was observed in insulin-induced hypoglycemia." (PMID 38026658, 2023). "In diabetic patients, hypoglycemia often occurs due to high doses of insulin." (PMID 37047250, 2023). "However, after partial remission, a progressively growing dependence on exogenous insulin induces an increased glycemic variability and the difficulty for patients to avoid hypoglycemia." (PMID 38033011, 2023). "Like case 1, the patient exhibited enhanced blood insulin during the hypoglycemia attacks." (PMID 37587407, 2023). "Furthermore, in either type 1 DM (T1D) or T2D subjects, treatment with insulin or insulin secretagogues can induce recurrent episodes of hypoglycemia, leading to brain neuronal dysfunction and increasing cognitive impairment and dementia development." (PMID 37174649, 2023). "Studies of pregnant sheep conducted found exposure to circadian disruption using a chronic shift work model (alternating light-dark patterns using 12-h shifts) resulted in hypoglycemia and decreased insulin sensitivity in response to an intravenous glucose tolerance test." (PMID 37727248, 2023). "Investigates cardiac responses to acute insulin-induced hypoglycemia in humans." (PMID 38022365, 2023). "The currently usable AID systems prevent hypoglycaemia by decreasing, and even suspending, the delivery of basal insulin, but this modality has limitations, related, for example, to the half-life of the insulin already injected and/or the delay in glucose sensing." (PMID 37685946, 2023). "If these changes do not suffice, medication treatment is recommended, starting with medications without risk of hypoglycaemia, followed by medication with risk of hypoglycaemia, up to administration of insulin." (PMID 37936205, 2023). "As this class of AHAs stimulate insulin release regardless of insulin levels, they come with a risk of hypoglycemia." (PMID 36789141, 2023). "Protein intake also stimulates insulin secretion but does not cause hypoglycemia, possibly because protein intake stimulates glucagon, which facilitates glycogenolysis in the liver." (PMID 38068304, 2023). "Each laboratory should therefore be aware of the limitations of their insulin assays, and if required, samples should be referred to the specialist laboratory using a quantitative mass spectrometry-based method to exclude factitious hypoglycaemia due to exogenous insulin administration." (PMID 37892096, 2023). "Examines the regulation of serum potassium during insulin-induced hypoglycemia." (PMID 38022365, 2023). "Thus, the presence of high plasma levels of AAs induces a strong glucagonotropic effect, preventing potential hypoglycemia due to AA-induced insulin secretion." (PMID 37635984, 2023).
Hypoglycemia (continued). "The SGLT2i have a mechanism of action not linked to insulin secretion, which makes the detrimental occurrence of hypoglycemia less likely compared to other classes of anti-diabetic drugs and also allows the achievement of steady levels of blood glucose." (PMID 37109151, 2023). "However few studies with metformin in clinical trials have reported increased ovulation rates with decreased basal insulin levels in normo insulinemic subjects indicating hypoglycaemia if prescribed to PCOS-NIR." (PMID 36932437, 2023). "Conversely, we speculated that incomplete lethality probably resulted from fish having a higher tolerance for hypoglycemia than mammals or that insulin signaling has divergent roles between fish and mammals." (PMID 37305084, 2023). "And two of these patients with actual HbA1c <7% but predicted HbA1c ≥7% had experienced hypoglycemia, one of them was given insulin treatment and the other one was given insulin secretagogues, compared with no one had experienced hypoglycemia in both actual and predicted HbA1c <7%." (PMID 36824358, 2023). "Lack of cortisol has been shown to increase insulin sensitivity, which will enhance peripheral tissue’s uptake of glucose, thereby increasing the risk of a hypoglycaemia event." (PMID 38053731, 2023). "Thus, the action of mini-doses of glucagon was blunted after an insulin bolus but preserved for hypoglycemia during low circulating insulin levels." (PMID 37334295, 2023). "However, the amount of additional insulin to be used with these meals still needs to be optimized to reduce the frequency of postprandial hypoglycemia." (PMID 40303273, 2023). "Our previous research has demonstrated that mice lacking functional growth hormone‐releasing hormone (GHRH) exhibit distinct physiological characteristics, including an extended lifespan, a preference for lipid utilization during rest, mild hypoglycemia, and heightened insulin sensitivity." (PMID 37667562, 2023). "Additionally, patients who are on insulin or insulin secretagogues should have fast-acting carbohydrates, such as candy, readily available to prevent hypoglycemia." (PMID 37686185, 2023). "The analyses of adverse outcomes at birth showed significantly lower birth weight and significantly increased risk of SGA associated with exposure to metformin, compared with insulin; combination treatment was associated with increased risk of LGA, preterm birth, and hypoglycemia." (PMID 37409227, 2023). "A meta-analysis of 13 RCTs demonstrated that short-acting insulin analogues provide better control of HbA1c and postprandial glucose in T2DM than regular human insulin, with no substantial reduction in the risk of severe hypoglycemia." (PMID 37264625, 2023). "Adolescents may require help eating or drinking to treat hypoglycemia and have to be supervised until the low values return to a normal range; sometimes, they need a reminder to self-administer insulin bolus at lunch." (PMID 37373970, 2023). "The incidence rate of hypoglycemia in this study was 2.3 per 1000 visits yearly; the admission rate was 3.9 per 10,000 visits yearly, with two-thirds of patients using insulin and almost exclusively using premixed insulin preparations." (PMID 37046876, 2023). "Moreover, we have previously shown that obese and insulin resistant individuals have an augmented cortisol axis response to hypoglycemia." (PMID 37400734, 2023). "Since the 1960s, the association among DM, cognitive dysfunction, and brain damage has been reported to be affiliated with recurrent hypoglycemia with low brain glucose concentration, secondary to pharmacological treatments for DM, especially insulin therapy in DM subjects." (PMID 38003671, 2023). "The increased insulin dose given before high-fat and protein meals could result in early postprandial hypoglycemia as the delayed gastric emptying induced by dietary fat produces a lag in glucose absorption." (PMID 40303273, 2023).
Hypoglycemia (continued). "In another study, ventricular arrhythmias were observed in association with asymptomatic hypoglycemia during simultaneous CGM and ECG recording for 5 days in patients with T2D and documented cardiovascular disease treated with insulin and/or sulfonylureas, particularly during the night." (PMID 37298308, 2023). "Based on these profiles, treatment with insulin degludec resulted in a lower risk of level 1 and level 2 nocturnal hypoglycemia compared to insulin glargine U100." (PMID 38089060, 2023). "Therefore, with the combination of clinical signs, repeated measurements of hypoglycemia (2.6 mmol/L), and an insulin level of 10 mIU/L, a diagnosis of insulinoma was considered highly likely." (PMID 38260191, 2023). "This is especially important for accidental or factitious insulin secretagogue-induced (e.g., sulphonylureas) hypoglycaemia, which may produce an identical clinical and biochemical picture to insulinoma." (PMID 37892096, 2023). "As with all insulin dose adjustments, safety should be maximized by making small adjustments at a time (10%–20%), and reevaluating after a few days (except in the case of marked hypoglycemia increase, in which case settings should be adjusted more imminently)." (PMID 37751154, 2023). "In studies where tirzepatide was assessed as monotherapy or combined with metformin and SGLT2 inhibitors, the occurrence of clinically significant (level 2 or severe) hypoglycaemia was rare, while hypoglycaemia was more common when tirzepatide was added to a sulfonylurea or insulin." (PMID 37509514, 2023). "Indeed, the previous study was performed in a context of early PN, in which most episodes of hypoglycemia were insulin-induced." (PMID 37365667, 2023). "If hypoglycemia was seen, the corresponding insulin titration was held." (PMID 38008775, 2023). "Hypoglycemia is especially prevalent in patients with type 1 diabetes (T1D) treated with exogenous insulin, or T2D being treated with oral sulfonylurea agents or exogenous insulin." (PMID 36830610, 2023). "Insulin had to be discontinued in this patient due to hypoglycemia." (PMID 37371827, 2023). "The blockade of KCNH6 channels with berberine increased insulin secretion, but only under hyperglycemic conditions, suggesting that berberine is a glucose-dependent insulin secretagogue that does not cause hypoglycemia or affects basal insulin secretion." (PMID 37513825, 2023). "Insulin-induced hypoglycemia is used to test central stimulation of adrenal function." (PMID 38068304, 2023). "The burst keywords that mainly focused on the mechanism (insulin-induced hypoglycemia, insulin, insulin degradation enzyme), and the change in the brain due to DACD (white matter lesions, central nervous system, hippocampal synaptic plasticity) began to explode in the beginning." (PMID 37575299, 2023). "Similarly, there is evidence for the beneficial effects of insulin secretagogues on GIH, but their use can be compromised by weight gain, hypoglycemia, and a possible increased cardiovascular risk." (PMID 37253115, 2023). "Furthermore, an in vivo analysis in diabetic rats revealed sustained hypoglycemia, demonstrating the potential efficacy of transferosomes in the transdermal delivery of insulin." (PMID 36979643, 2023). "Thus, the effect of IGF-1 on glucose metabolism is similar to insulin (insulin-like effect) and—in contrast to GH—promotes hypoglycaemia." (PMID 37895086, 2023). "When hypoglycaemia becomes manifest, hospital admission can be avoided through rapid intake of sugar-containing foods or drinks or through glucagon intake (an antagonist of insulin, e.g. as a nasal spray)." (PMID 37408713, 2023). "Height, systolic blood pressure, total daily insulin dose, basal/total insulin dose, and time in hypoglycemia were positively correlated to sweat response, while low-density lipoprotein, and HbA1c (mean of the previous 5 years) were negatively correlated to sweat response (all p values < 0.05)." (PMID 37682387, 2023).
Hypoglycemia (continued). "Further work would be required to delineate whether histaminergic neuron activation in these conditions was mediated by the hypoglycemia or insulin itself." (PMID 37448468, 2023). "Counter-regulatory hormones such as cortisol and glucagon are important in the acute response to neonatal hypoglycaemia and may have a role in determining longer-term insulin sensitivity in childhood." (PMID 37442824, 2023). "Therefore, the elevated baseline V ̇E during the insulin induced‐hypoglycaemia is the result of a highly sensitive counter‐regulatory response to activate the autonomic nervous system to normalize the elevated metabolic rate and altered arterial blood gases." (PMID 36459572, 2023). "Finally, we did not observe a correlation between the rest of the studied variables (therapeutic education, the types of insulin therapies, hypoglycemia and complications of the disease in patients diagnosed with T1D) with the PA performed by the participants." (PMID 37491278, 2023). "However, despite the increased abundance of α cells, glucagon secretion (like insulin secretion) is impaired in CF, in response to a range of stimuli including arginine and hypoglycemia." (PMID 38075070, 2023). "Pioglitazone does not increase insulin secretion and acts only in its presence, and does not cause hypoglycemia." (PMID 38276837, 2023). "However, the amount of additional insulin used needs optimization to reduce the frequency of postprandial hypoglycemia." (PMID 40303273, 2023). "Notably, though, the addition of physiological parameters, such as insulin dosing, only marginally improved the prediction of hypoglycemia in certain predictions." (PMID 36719713, 2023). "On the low GI diet, the incidence of moderate hypoglycemia was considerably greater than on the high GI diet, suggesting that insulin doses may need to be decreased even more with low GI meals." (PMID 38111457, 2023). "Incipient hypoglycemia triggers a cascade of protective responses, including the suppression of endogenous insulin, stimulation of glucagon secretion, and sympatho-adrenal activation, thus increasing endogenous glucose production and reducing glucose disposal to restore normal glycemia levels." (PMID 37327258, 2023). "Most of the literature published to date regarding management of euglycemic DKA is centered on using standardized DKA treatments with IV fluids, insulin infusions, and electrolyte management, with the added caveat that glucose will need to be added to fluids early to prevent hypoglycemia." (PMID 38165186, 2023). "Loss-of-function pathogenic variants in KCNJ11 (the gene that encodes Kir6.2) can lead to congenital hyperinsulinism (CHI), a disorder characterized by persistent β-cell depolarization which results in excessive insulin secretion even in the presence of severe hypoglycemia." (PMID 37408765, 2023). "In conclusion, this study shows that standing in cool water at 23 °C or thermoneutral water while blood insulin is at a basal or near basal level does not increase the risk of hypoglycemia during and early after immersion in water." (PMID 37942293, 2023). "Another open-label randomized control study on 20 adults with T1D showed that treatment with insulin degludec was associated with a lower coefficient of variation without significant difference in hypoglycemia than insulin glargine." (PMID 36800034, 2023). "This observed hypoglycemia could be due to more insulin in circulation as a result of reduced insulin sensitivity and/or higher glucose levels during this phase of the menstrual cycle, as previously reported." (PMID 36833469, 2023). "The degradation of insulin granules by GOMED was also observed in hypoglycemia-induced mice." (PMID 38132137, 2023). "MiniMed 640G suspends the basal insulin infusion with the hypoglycemia prediction algorithm." (PMID 36769430, 2023).